TNF (tumor necrosis factor)
Diseases named in the same sentence as TNF in open-access papers (continued):
Sharing a sentence is not in itself a finding about the gene and the disease.
psoriasis (continued). "IL-6, TNF-α, IL-23, and IL-17 levels significantly increased in IMQ-induced mice with psoriasis (p < 0.01)." (PMID 36992832, 2023). "We also treated HMEC-1 cells with psoriasis-related cytokines such as IL-17A, IL-22, IL-25, IFN-γ, TNF-α, and, VEGF-A, and among them, IFN-γ significantly upregulated the expression and secretion of IGFBP7 in HMEC-1 cells." (PMID 36917196, 2023). "This mediator reduces the levels of pro-inflammatory cytokines such as TNFα and INFγ, which appear to be involved in CHE and several other diseases like psoriasis." (PMID 38203533, 2023). "Silencing of PARP2 in human keratinocytes prevented their hyperproliferation, maintained their terminal differentiation, and reduced their production of inflammatory mediators after treatment with psoriasis-mimicking cytokines IL17A and TNFα." (PMID 37351597, 2023). "It was observed a 7-fold reduction of TNF-α expression and a synergic effect between tacrolimus and TNF-α siRNA, successfully treated psoriasis in the in vivo model." (PMID 37376042, 2023). "Through the activation of the JAK/STAT and Notch signaling pathways, together with their downstream effector molecules including TNF-α, IFN-γ, IL-17, TGF-β, these subsets of Th cells are then deeply involved in the pathogenesis of psoriasis." (PMID 37270497, 2023). "Because of the shared genetic and immunologic features of psoriasis and IBD, certain classes of biologic therapy are nowadays used to control flares for both diseases, especially TNF-alpha inhibitors, ustekinumab, and IL-23 inhibitors." (PMID 37631384, 2023). "TNF-α-induced NF-κB pathway activation plays a part in psoriasis, and TNF-α monoclonal antibodies have been employed in clinical settings for psoriasis treatment." (PMID 38007430, 2023). "The characteristic inflammation and hyperproliferation of keratinocytes in psoriasis is regulated by progranulin (PGRN), which suppresses the expression and release of inflammatory cytokines, such as TNF-α." (PMID 38129828, 2023). "Both paradoxical worsening of IBD and new-onset cases induced by anti-TNF-α agents have been reported in patients with different inflammatory diseases, especially AS, JIA, and psoriasis." (PMID 37175894, 2023). "The nanoformulations of CUR were majorly able to decrease psoriasis inflammatory symptoms, PASI, TNF-α, IL-17, IL-22 and IL-1β levels, C-C chemokine receptor type 6 (CCR6) expression, the proliferation of psoriatic cells and occurrence of psoriatic lesions." (PMID 36678859, 2023). "Through intragastric administration, CUR can alleviate psoriasis‐like lesions of mice by decreasing PASI scores, reducing the level of IL‐6, IL‐17A, IL‐22, IL‐23, TNF‐α, and TGF‐β1, promoting the expression of IL‐10." (PMID 37647442, 2023). "Various inflammatory cytokines, such as tumor necrosis factor (TNF)-α, interleukin (IL)-12, interleukin (IL)-17, IL-22, and IL-23 and interferon (IFN)-γ, contribute to the immunopathogenesis of psoriasis." (PMID 37334353, 2023). "Serum cytokines, including TNF-α, IFN-γ, IL-2, IL-6, IL-22, and IL-23, are primarily produced by Th1 and Th17 cells and have emerged as potential biomarkers for psoriasis." (PMID 38239345, 2023). "The serum levels of TNF-α and IL-17 were synergistically elevated by the co-occurrence of NASH and psoriasis." (PMID 37646025, 2023). "TNF-a is a crucial factor in immune-related conditions such as RA, AS, inflammatory bowel disease (IBD), psoriasis, and hidradenitis suppurativa (HS)." (PMID 37942312, 2023). "The combination of TNF-α, IL-1α, IL-17A, IL-22, and OSM (termed as M5) has been shown to induce psoriasis-like changes, including cell inflammation and increased cell proliferation in cultured keratinocytes." (PMID 36999136, 2023). "A significant up regulation in lncRNA NEAT, TNF-α, VEGF genes expression (p value˂0.001) in psoriasis patients in addition to significant increase in ROS and caspase-3 levels (p value˂0.001) in compare to controls." (PMID 37531036, 2023).
psoriasis (continued). "The process results in producing pro-inflammatory cytokines such as interferon (IFN)-α, tumor necrosis factor (TNF)-α, interleukin (IL)-12, IL-20, and IL-23, and initiates the early phase of cutaneous inflammation in psoriasis." (PMID 37108492, 2023). "TNFα alone, or in concert with IL17A, acts mainly through the activation of NF-κB, a critical pro-inflammatory pathway in the development of psoriasis." (PMID 37351597, 2023). "We herein analyze the transition of the NLR, MLR, PLR or CRP during the treatment with TNF-α inhibitors, IFX, ADA and CZP in patients with psoriasis and tried to determine which of the parameters can act as biomarkers reflecting the treatment response." (PMID 36769622, 2023). "The subsets of T lymphocytes intensely studied in psoriasis are CD4+ T helper 1, T helper 17, and T helper 22, which secrete TNFα/IFNγ, IL-17/Il-22, as well as IL-22, respectively." (PMID 37631384, 2023). "As demonstrated in an in vitro model of psoriasis, DHA supplementation rebalances PPAR receptor expression and results in decreased TNF‐α secretion, thereby restoring the differentiation and proliferation of epidermal cells and reducing inflammation." (PMID 37823124, 2023). "TNF-α and IL-17A both play a major role in inducing keratinocyte MAPK pathway activation in patients with psoriasis." (PMID 37686332, 2023). "The data in our study showed that glycyrrhizic acid compound ointment inhibited inflammatory cytokines including TNF-α, IL-12, IL-17A, and IL-23 in the skin of IMQ-induced psoriasis-like mice, and the inhibitory effect became stronger with increasing dose." (PMID 37643205, 2023). "The recruitment of circulating leukocytes to the epidermis and the production of pro-inflammatory factors, such as TNF-α, IFN-γ, IL-6, IL-8, IL-23, IL-1β, and IL-17A play a crucial role in the development of psoriasis." (PMID 37346040, 2023). "So far, studies have been published on survival of the various BTs from clinical practice records in patients diagnosed with psoriasis, and longer survival has been found with the IL-12 and IL-23 inhibitor drug (anti-IL-12/23, UTK) compared to anti-TNF drugs." (PMID 37240048, 2023). "Six types of drugs are covered in our dataset for psoriasis treatment, including MTX, topical corticosteroid (TCS), acitretin, tumor necrosis factor alpha (TNF-α) inhibitors, interleukin-17 (IL-17) inhibitors, and interleukin-23 (IL-23) inhibitors." (PMID 36732611, 2023). "TRAPPC9 was reported to be a predictive marker for failure in patients treated with TNF-α inhibitors and REV3L was found to be a candidate target gene for psoriasis and PsA treatment/therapy." (PMID 38003284, 2023). "Previous clinical studies have confirmed that oral BZLF can effectively improve the PASI score and reduce serum levels of TNF-α and VEGF in patients with psoriasis." (PMID 36950008, 2023). "The first case of paradoxical psoriasis induced by TNF-α inhibitors was reported in 2004, but with increasing usage of TNF-α inhibitors, more cases are being reported." (PMID 37664349, 2023). "The pathogenesis of psoriasis is influenced by dysfunction within specific T cell subsets, leading to the aberrant release of corresponding cytokines, including IFN-γ, TNF-α, IL-23, and the members of the IL-17 family." (PMID 38239345, 2023). "As an effective tumor necrosis factor-alpha (TNF-α) inhibitor, etanercept has been used for the treatment of psoriasis." (PMID 37113086, 2023). "In previous studies, tumor necrosis factor-alpha (TNF-α) emerged as a pivotal factor in the emergence of chronic inflammatory skin diseases, including systemic lupus erythematosus and psoriasis." (PMID 38239345, 2023). "The results showed that IL-17A and TNF-α, as two key genes of the TNF-α/IL-23/Th17 axis, are upregulated m6A methylation in skin lesions of psoriasis patients." (PMID 37124930, 2023).
psoriasis (continued). "TNF-α and both Th17 (IL-17 and IL-22) and Th1 (IFN-γ) cytokines activate keratinocytes proliferation and angiogenesis, two key features in psoriasis pathogenesis." (PMID 37372997, 2023). "The aberrant type 1/17 immune responses represent a predominant mechanism in psoriasis due to the abundant release of type 1/17 cytokines such as IFN-γ, IL-17A, IL-23, and tumor necrosis factor (TNF)-α." (PMID 37259392, 2023). "Circulating blood levels and titer in skin lesions of TH1 cytokines (e.g., IFNγ, IL-2, TNFα) and TH17 cytokines (e.g., IL17A, IL17F, IL22, IL26) are significantly increasedin active psoriasis, as well as eruptive lesion IL23, IL20 and IL15." (PMID 37885781, 2023). "In this study, 379 lines of treatment (anti-TNF: 247 and UTK: 132) in 198 patients diagnosed with moderate-to-severe psoriasis were evaluated to determine the influence of SNPs in functional genes on drug survival." (PMID 37240048, 2023). "Using HaCaT cells, it was shown that metformin inhibits the expression of inflammatory cytokines (IL-6 and TNF-α) and downregulates the growth factor VEGF thus inhibiting the inflammatory response in psoriasis by inhibiting mTOR." (PMID 37371141, 2023). "There are currently 11 biologics in four different classes (anti-TNF-α, anti-IL12/23, anti-IL17, and anti-IL23p19) approved by the FDA for psoriasis treatment." (PMID 38003284, 2023). "Studies indicated that acitretin did not increase risk of viral or respiratory infections in psoriasis patients, and the rates of COVID-19 infection and hospitalization in psoriasis patients exposed to acitretin were similar to that of exposure to TNF inhibitors." (PMID 36389759, 2022). "The increased levels of inflammatory markers, such as tumor necrosis factor-α (TNF-α), interleukin-6, and C-reactive protein, have indeed been found in the lung tissue of patients with psoriasis." (PMID 35163689, 2022). "Meta-analysis showed that EAHM had superior effects compared to the control group in PASI 70, PASI 60, continuous PASI score, IL-17, TNF-α, and DLQI of psoriasis patients." (PMID 35745164, 2022). "The first class of biologics comprises anti-tumor necrosis factor (anti-TNF) agents, including infliximab, adalimumab (ADM), etanercept and golimumab, which remain widely used in psoriasis, in addition to psoriatic arthritis and inflammatory bowel disease." (PMID 35683398, 2022). "We found that subcutaneous application of umbilical cord- derived mesenchymal stem/stromal cells (MSCs) primed by IFN-γ and TNF-α, referred to as MSCs-IT, exhibited remarkable therapeutic efficacy on imiquimod (IMQ)-induced psoriasis-like inflammation in mice." (PMID 36433947, 2022). "This work evaluated the expression levels of the circulating miR-203 target genes SOCS3, SOCS6, TP63, TNF-, IL8, and IL24 in psoriasis patients." (PMID 36341243, 2022). "Our data show that eCIRP expression was increased in the sera of psoriasis patients and imiquimod- (IMQ-) induced psoriatic mice and cells stimulated with proinflammatory cytokines (IL-1α, IL-17A, IL-22, oncostatin M, and TNF-α; mix M5)." (PMID 36110097, 2022). "Inflammation-related factors such as TNF, IL6, and IL1β were abnormal throughout the pathogenesis of psoriasis." (PMID 35265149, 2022). "Psoriasis and CAD are however known to share certain cytokines, including IFNγ, TNF, IL-6, and IL-1793,94." (PMID 36323703, 2022). "Under the condition of abundant IL-23 in psoriasis lesional skin, some macrophages possibly produce IL-17A, IL-22 and IFN-γ in addition to TNF-α." (PMID 35837394, 2022). "In the pathogenesis of psoriasis, PRINS inhibits the expression of cellular inflammatory factors [e.g., interleukin (IL)-1α, IL-1β, IL-6, IL-8, and tumor necrosis factor-α) and thus affects inflammatory responses." (PMID 36187126, 2022). "The tumor necrosis factor (TNF) gene has over 200 variations, four of which were intensively investigated in psoriasis due to their relevance to the disease's physiopathology." (PMID 35035485, 2022).
psoriasis (continued). "Lastly, IL-37 is able to inhibit IL-1β, IL-6, TNF, and chemokines such as CCL2, all involved in psoriasis." (PMID 36012744, 2022). "During this process, inflammatory cytokines: TNF‐α, IL‐1β, IL‐6, IL‐17a, and CXCL‐15 were infiltrated in skin and contributed to psoriasis." (PMID 35281792, 2022). "In psoriasis, interferon-γ (IFN-γ), IL-17α, TNFα, and IL-22 can induce keratinocytes to produce more chemokines and cytokines in a self-amplifying loop." (PMID 35742957, 2022). "Recent advances in understanding molecular and cellular pathways have identified tumor necrosis factor-α (TNF-α), interleukin-17 (IL-17), IL-23, IL-22 as major contributors in psoriasis pathogenesis." (PMID 35265634, 2022). "The role of these cytokines in chronic inflammatory diseases, such as RA, psoriasis and IBD, has been extensively studied and anti-TNFα and IL-Inhibitors have led to important changes in clinical practice." (PMID 36579506, 2022). "The development of biological agents, such as anti-TNFα, anti-IL17 and anti-IL23 antibodies offers a potentially safer and long-term option for patients with moderate-to-severe psoriasis." (PMID 36428539, 2022). "PAR1 signaling stimulates the expression of various growth factors in macrophages and is also involved in psoriasis via the activation of STAT3, which can stimulate TNF-α, IL-23, and IL-17 production." (PMID 36552865, 2022). "TNF-α inhibitors induce a marked improvement in the skin and joint symptoms of psoriasis, while in HCV-infected individuals, persistent inflammation mediated by TNF-α leads to liver cirrhosis and metabolic disorders." (PMID 35805960, 2022). "Despite the close relationship between psoriasis and IBD, there has been little data on the paradoxical development of psoriasis after anti-TNF treatment in IBD patients." (PMID 35801760, 2022). "The release of cytokines, such as IL-1β and TNF-α/IL-23/IL-17 by TLR4-mediated inflammatory immune cells is related to the severity of psoriasis." (PMID 36382932, 2022). "The TNF/IL23/IL17A axis was also widely involved in the body's immune response, promoting the occurrence of psoriasis inflammatory response and the proliferation of epidermal cells." (PMID 35265149, 2022). "The occurrence and severity of psoriasis has alsoreported in patients with obesity where an increased level of Osteopontin (OPN), TNF, CCL5 and CXCL9 levels are documented." (PMID 36518145, 2022). "Dendritic cells are the source of cytokines (TNF-α, IFN-γ, etc.)that play a crucial role in the pathogenesis of psoriasis." (PMID 35729678, 2022). "In the case of psoriasis, various studies on systemic inflammation and its circulating markers like high sensitivity C-reactive protein (CRP), tumor necrosis factor-alpha, and interleukin-6 are seen in the picture." (PMID 36106203, 2022). "At present, most monoclonal antibody preparations were aimed at this mechanism and block downstream inflammatory mediators such as TNF and IL17A to treat psoriasis." (PMID 35265149, 2022). "Nevertheless, it still contributes to the psoriasis cytokine storm; hence, other postulations suggested that IFN-γ is synergic with TNF-α." (PMID 35203707, 2022). "A further investigation of the effect of compounds 1 on psoriasis showed a dramatic decrease in the levels of chemokines, CCL8 and CCL20 in the TNF-α/IL-17/IFN-γ-induced HaCaT psoriasis model." (PMID 36015080, 2022). "Activated Th1 cells can produce proinflammatory molecules, TNF-α and IFN-γ, and interact with dendritic cells to trigger type 1 inflammation in psoriasis." (PMID 35209199, 2022). "Clinical management of psoriasis and psoriatic arthritis has been transformed by the introduction of biologics, starting with infliximab (IFX), an anti‐TNFα antibody." (PMID 35799412, 2022). "T lymphocytes are widely represented in psoriasis-induced skin lesions and are responsible for the release of IFN-γ, TNF-α, and IL-17." (PMID 35335319, 2022).
psoriasis (continued). "The co-administration of IL-33 with the peptide substance P (SP) significantly increases the expression and secretion of TNF and VEGF in MCs, further promoting angiogenesis and increasing inflammation in psoriasis." (PMID 36405690, 2022). "The pathogenesis of psoriasis includes excessive proinflammatory cytokines, such as IFN-γ, TNF-α, IL-17, IL-22, and IL-23, among which IL-17A plays a key role." (PMID 35745784, 2022). "In addition to TNF-α, the levels of other factors, such as cathelicidin, TLR9, and IFN-γ, are increased in HCV-infected individuals, thus providing further evidence that HCV infection may predispose patients to developing psoriasis." (PMID 35805960, 2022). "In conclusion, drug survival of UST was significantly higher than that of TNF-alpha inhibitors and SEC in treatment of psoriasis." (PMID 34365780, 2022). "In 2010, the National Psoriasis Foundation Medical Board only recommended the cautious use of anti-TNF-α inhibitors in closely monitored patients with HIV and very refractory psoriasis or debilitating psoriatic arthritis." (PMID 35990692, 2022). "In the current study, elevated levels of proinflammatory molecules TNF-α and IL-1β were observed in the prefrontal cortex of IMQ-induced psoriasis mice." (PMID 35209199, 2022). "As a conclusion, drug survival of UST was significantly higher than that of TNF-alpha inhibitors and SEC in the treatment of psoriasis." (PMID 34365780, 2022). "TNF-α and IL-6 mRNA expressions were reduced in the skin lesions of mice with C23-treated IMQ-induced psoriasis, and this effect was accompanied by inhibition of the NF-κB and ERK1/2 signaling pathways." (PMID 36110097, 2022). "In patients with psoriasis, the antagonism of TNF-α with etanercept also reduced the circulating levels of inflammatory and cardiovascular proteins, such as TNF-α, IL-1β, IL-6, and IL-8." (PMID 34674004, 2022). "The association between TNF-α inhibitors and psoriasiform eruptions was first suggested in a study of a cohort of 107 patients with spondyloarthropathy that were treated with infliximab, in which three patients without a personal or family history of psoriasis developed palmoplantar pustulosis." (PMID 35884790, 2022). "These anti-TNF biologics are currently used successfully for the clinical treatment of RA, JIA, PsA, ankylosing spondylitis, psoriasis, and forms of IBD, particularly Crohn’s disease (CD) and ulcerative colitis (UC)." (PMID 36467083, 2022). "Moreover, the concentrations of IFN-γ, TNF-α, IL-17A, and IL-23 in skin lesions and serum of mice decreased significantly, suggesting that hUC-MSCs and indirubin are involved in the process of immune regulation in the treatment of psoriasis, and the targets and focuses are different." (PMID 36466901, 2022). "Regarding psoriasis exclusively, researchers found that the levels of GCF TNF-α were significantly higher in psoriatic patients compared to healthy controls." (PMID 35454992, 2022). "Another psoriasis-like model was generated through stimulation of a 3D HSE with interlukin-17A (IL-17A), interlukin-22 (IL-22), and tumor necrosis factor α (TNFα)." (PMID 35214050, 2022). "For psoriasis targets, most phase III trials studied TNF-α (n = 7), IL-17 (n = 2), and IL-23 (n = 1)." (PMID 35529441, 2022). "Two proteomic studies comparing HS with psoriasis found a greater serum inflammatory burden, a more TH1/TH17-skewed cytokine profile, and a high TNF-α signature in comparison with psoriasis." (PMID 36092908, 2022). "The expression of elastin gene can be enhanced by various factors increased in both psoriasis and during aging, including TGF-β, TNF-α, and elastin fragments." (PMID 35625870, 2022). "Elevated levels of TNF-α, IL-2, and INF-γ, and reduced levels of IL-10 in psoriasis compared to the control group." (PMID 35454992, 2022). "Except for TNF-α, another member of TNF superfamily, TNF-like weak inducer of apoptosis (TWEAK) has recently been identified as a key cytokine in psoriasis." (PMID 35075118, 2022).